CYBB (cytochrome b-245 beta chain)
Diseases named in the same sentence as CYBB in open-access papers (continued):
Sharing a sentence is not in itself a finding about the gene and the disease.
Crohn disease (6 papers, 2015 to 2025). A gastrointestinal disorder characterized by chronic inflammation involving all layers of the intestinal wall, noncaseating granulomas affecting the intestinal wall and regional lymph nodes, and transmural fibrosis. "The initial screening for pathogenic variants in established monogenic IBD genes identified a nonsense mutation in CYBB (p.W380X) in a 31-year-old male patient of European descent with infantile-onset of granulomatous colitis, perianal abscesses and hidradenitis suppurativa." (PMID 32081864, 2020).
glioblastoma (6 papers, 2015 to 2026). The most malignant astrocytic tumor (WHO grade IV). "Temozolomide (TMZ)-resistant glioblastoma multiforme (GBM) cells exhibit mesenchymal and stemness traits and resist erastin-induced ferroptosis by activating the CYBB/NRF2/SOD2 pathway." (PMID 41601687, 2026). "Furthermore, cytochrome b-245 beta chain (CYBB), a subunit of NADPH oxidase, interacts with NRF2 and promotes temozolomide resistance by regulating the NRF2-SOD2 axis in mesenchymal glioblastoma." (PMID 39624080, 2024).
lung carcinoma (6 papers, 2011 to 2022). "CYBB is a primary component of the microbicidal oxidase system of phagocytes and associated with smoking risk factors in patients with lung adenocarcinoma, which is involved in encoding NOX2 to promote lung cancer metastasis." (PMID 33312950, 2020).
pancreatic cancer (6 papers, 2020 to 2025). "In the microenvironment of pancreatic cancer, tumor cells induce the downregulation of CYBB in macrophages (such as U937 cells), promoting the polarization of macrophages towards the M2 phenotype (an anti-inflammatory/tumor-promoting phenotype)." (PMID 40692778, 2025).
diabetic nephropathy (5 papers, 2019 to 2022). "CYBB promotes macrophage infiltration in diabetic kidney disease; conversely, inhibition of NOX2 attenuates podocyte injury and oxidative stress." (PMID 35601837, 2022).
osteosarcoma (5 papers, 2021 to 2025). A usually aggressive malignant bone-forming mesenchymal neoplasm, predominantly affecting adolescents and young adults. "Conversely, CYBB overexpression led to poor prognosis of osteosarcoma." (PMID 36386203, 2022). "Consistent with our observations from TCGA and GTEx, most hub genes—including PLEK, CYBB, CXCR4, and ITGAM—were significantly upregulated in osteosarcoma samples compared to normal controls." (PMID 40895569, 2025).
silicosis (5 papers, 2019 to 2025). Silicosis is a respiratory disease caused by breathing in (inhaling) silica dust. "In the present study, lungs of rat model of silicosis showed increased phagocyte NADPH oxidase activity with upregulated five structural components NOX2 (CYBB), p22phox (CYBA), p47phox (NCF1), p67phox (NCF2) and p40phox (NCF4)." (PMID 34991559, 2022).
periodontitis (4 papers, 2022 to 2026). An acute or chronic inflammatory process that affects the tissues that surround and support the teeth. "In addition, correlation analysis showed that CD53, CYBB, and PLEK were significantly positively linked with activated CD4+T cells in the immune microenvironment of peri‐implantitis, making them effective biomarkers to differentiate it from periodontitis." (PMID 38780047, 2024).
arteriosclerosis (3 papers, 2018 to 2023). A vascular disorder characterized by thickening and hardening of the walls of the arteries. "At first glance, it is surprising since increased ROS production and oxidative stress are generally associated with arteriosclerosis and cardiovascular disease, and pharmacological inhibition of CYBB is associated with a delayed atherosclerotic progression in animal models." (PMID 31756991, 2019).
Chronic colitis (3 papers, 2013 to 2022). A chronic inflammatory disease of the large intestine (colon, cecum and rectum). "Further, the expression of NAMPT and CYBB markedly increased in association with increased disease severity in normal mice or those with acute or chronic colitis." (PMID 36552583, 2022). "rCT-NAMPT effectively suppressed the severity of disease in DSS-induced acute and chronic colitis models through targeting the colon and inhibiting the interaction of NAMPT with CYBB or TLR4." (PMID 36552583, 2022).
Cirrhosis (3 papers, 2019 to 2026). A chronic disorder of the liver in which liver tissue becomes scarred and is partially replaced by regenerative nodules and fibrotic tissue resulting in loss of liver function. "It was demonstrated that the expression level of CYBB was significantly upregulated in HE samples when compared to health control samples and cirrhosis samples, respectively." (PMID 36424620, 2022). "Meanwhile, CYBB was also capable of distinguishing between HE and cirrhosis (AUC = 0.974)." (PMID 36424620, 2022). "CYBB and FOXO1 might be major regulators during the development from cirrhosis to HE." (PMID 36424620, 2022).
cystitis (3 papers, 2022 to 2025). Inflammation of the urinary bladder. "In the model of bladder infection, mice with NOX2 (CYBB) deficiency are unable to effectively inhibit the NF-κB signaling pathway due to insufficient production of reactive oxygen species (ROS)." (PMID 40692778, 2025).
kidney failure (3 papers, 2019 to 2025). An acute or chronic condition that is characterized by the inability of the kidneys to adequately filter the blood. "In addition, there was a significant increase in the mRNA and protein levels of cytochrome b-245 heavy chain (Cybb) (protein: CYBB; also known as NADPH oxidase or NOX2), indicating stimulation of oxidative stress with kidney failure." (PMID 39946208, 2025).
type 1 diabetes (3 papers, 2015 to 2024). "Some studies have listed CYBB as a gene related to inflammation associated with kidney disease in type 1 diabetes." (PMID 38956704, 2024).
X-linked disease (3 papers, 2017 to 2024). X-linked form of disease. "A 16-year-old boy with a mutation in CYBB gene coding gp91phox protein (X-linked disease) developed a liver abscess due to Staphylococcus aureus." (PMID 28168067, 2017).
cervical squamous cell carcinoma (2 papers, 2019 to 2022). A squamous cell carcinoma arising from the cervical epithelium. "Notably, for histological type, CAMK2A, CYBB, IL1A, IL1B, and SLC25A5 were found to be upregulated in patients with cervical squamous cell carcinoma compared with those having cervical adenosquamous carcinoma (P < 0.05)." (PMID 36253777, 2022).
enteropathy (2 papers, 2013 to 2025). "In some patients, additional mutations in genes such as CYBB have been identified, contributing to atypical phenotypes characterized by immune dysregulation and severe enteropathy." (PMID 40963632, 2025).
leishmaniasis (2 papers, 2023 to 2024). Infectious disease that is transmitted through the bite of hematophagous female phlebotomine sand flies. "Among these 14 pathways, four major pathways were enriched: SNARE interactions involved in the vesicular transport (BET1 and STX6), leishmaniasis (FCGR1A, CYBB, and FOS), hematopoietic cell lineages (FCGR1A, ITGA3, MME, and CD5) and Fanconi anemia pathway (SLX4, ATR, and TELO2)." (PMID 37601105, 2023).
multiple myeloma (2 papers, 2021 to 2022). "Moreover, compared to normal bone marrow plasma cells, patients with MGUS, or a smoldering myeloma, NOX2 (encoded by CYBB) is the only catalytic subunit expressed in MM patients along with the p40phox (NCF4) and p22phox (CYBA) regulatory subunits." (PMID 34067602, 2021).
myeloproliferative neoplasm (2 papers, 2022 to 2023). A clonal hematopoietic stem cell disorder, characterized by proliferation in the bone marrow of one or more of the myeloid (i.e., granulocytic, erythroid, megakaryocytic, and mast cell) lineages. "Some authors found that CYBB was upregulated in Chronic Myeloid Leukemia (CML), while it served as a prognostic and diagnostic marker in myeloproliferative neoplasms (MPN)." (PMID 37629695, 2023).
nasal polyp (2 papers, 2021 to 2022). "The western blot results showed the expression level of ALOX5AP, BTK, CYBB, NCF2, HCK, and HK3 in CRSwNP was significantly increased in nasal polyps compared to control subjects." (PMID 33603773, 2021). "We found that ALOX5AP, BCL2A1, BTK, CYBB, NCF2, HCK, and HK3 were broadly expressed on both epithelial layer and stromal layer in nasal polyp tissues." (PMID 33603773, 2021). "Our study has proved the increased expression of ALOX5AP, BCL2A1, BTK, CYBB, NCF2, HCK, and HK3 by mRNA and protein levels in nasal polyps." (PMID 33603773, 2021). "Next, we identified the protein level of the seven hub genes (ALOX5AP, BCL2A1, BTK, CYBB, NCF2, HCK, and HK3) from nasal polyps from CRSwNPs and nasal mucosa from healthy controls." (PMID 33603773, 2021). "Moreover, the immunohistochemistry stain results also demonstrated that the protein level of ALOX5AP, BCL2A1, BTK, CYBB, NCF2, HCK, and HK3 were significantly increased in nasal polyps compared to control subjects." (PMID 33603773, 2021).
basal cell carcinoma (1 paper, 2022). A carcinoma involving the basal cells. "Genes in the low-expression cohorts of CD14, CYBB, NOD2, and TLR1 were all highly enriched in olfactory transduction, linoleic acid metabolism, and basal cell carcinoma." (PMID 36193326, 2022).
biliary atresia (1 paper, 2020). A rare, biliary tract disease characterized by progressive obliterative cholangiopathy of the intra- and extrahepatic bile ducts, occurring in the embryonic/ perinatal period, leading to severe and persistent neonatal jaundice and acholic stool. "It has been reported that biliary atresia patients with higher CYBB expression levels had higher risk of LC38, suggesting the association between CYBB and LC." (PMID 32968147, 2020).
bronchopulmonary dysplasia (1 paper, 2025). Bronchopulmonary dysplasia is a chronic respiratory disease that results from complications related to lung injury during the treatment of infant acute respiratory distress syndrome in low-birth-weight premature infants or from abnormal lung development in older infants. "In the model of bronchopulmonary dysplasia (BPD), the expression of CYBB in alveolar M1 macrophages decreases, leading to the impairment of their pro-inflammatory functions." (PMID 40692778, 2025).
hemophagocytic lymphohistiocytosis (1 paper, 2023). "In that regard, mutations in a number of immune-regulatory genes have been described in MIS-C, including SOCS1, XIAP, and CYBB as well as HLA class I alleles and rare heterozygous mutations in genes associated with hemophagocytic lymphohistiocytosis." (PMID 36282598, 2023).
ischemic disease (1 paper, 2023). Lack of blood supply to an area of the body, resulting in impairment of tissue oxygenation. "Currently, studies on the co-effects of NCF2 and CYBB on ROS are mainly seen in autoimmune, infectious, and ischemic diseases." (PMID 36671813, 2023).
Kawasaki disease (1 paper, 2022). A rare inflammatory disease characterized by an acute febrile, systemic, self-limiting, medium-vessel vasculitis primarily affecting children. "MPO showed association with the products of three Kawasaki disease genes (FCGR2A, CASP3, and LTA) and one related to MIS-C (CYBB)." (PMID 36510129, 2022).
lipid metabolism disorders (1 paper, 2025). "The inhibition of CYBB in zebrafish embryos leads to lipid metabolism disorders and excessive activation of the TLR4/NF-κB pathway, triggering liver injury and immune-inflammatory responses." (PMID 40692778, 2025).
osteonecrosis (1 paper, 2022). A none disease characterized by death of bone tissue due to a lack of blood supply. "Furthermore, miRNAs and TFs targeting CD14, CYBB, NOD2, and TLR1 were predicted and a total of 20 differentially expressed miRNAs were identified in patients with osteonecrosis and controls." (PMID 36193326, 2022).
pulmonary sarcoidosis (1 paper, 2024). Sarcoidosis affecting the lung parenchyma. "CTSS, CYBB, FPR2, MNDA, TLR1, and TLR8 could be conducive to improving the diagnostic process and understanding the underlying mechanisms of pulmonary sarcoidosis." (PMID 39364409, 2024). "CTSS, CYBB, FPR2, MNDA, TLR1, and TLR8 could be conducive to improving the diagnostic process and understanding the underlying mechanisms of pulmonary sarcoidosis, and were further verified in PBMC samples using qRT-PCR." (PMID 39364409, 2024).
schwannoma (1 paper, 2025). A benign, usually encapsulated slow growing tumor composed of Schwann cells. "Similarly, CYBB, commonly linked to oxidative burst in phagocytes, and ADIPOQ, associated with metabolic and inflammatory signaling, have not been connected to schwannoma biology." (PMID 41231782, 2025).
infection (163 papers, 2006 to 2025). The state of being infected such as from the introduction of a foreign agent such as serum, vaccine, antigenic substance or organism. "Strikingly, the same pattern as in NLRC4-deficient mice was observed in CYBB-deficient mice: 72 h after S. TmWT infection the epithelial barrier collapsed while after 72 h of S. TmSPI2 infection the epithelial barrier remained intact." (PMID 41370284, 2025). "A total of 117 cases of infection in the 100 patients were identified (100 associated with CYBB, 10 with CYBA, 3 with NCF1 and 1 with NCF2 mutations), and all had experienced at least 1 infectious episode (IQR 1–3)." (PMID 33168948, 2020). "This review will focus on how bacterial pathogens alter host epigenetics, by specifically examining A. phagocytophilum AnkA cis-regulation of CYBB transcription and epigenetic changes associated with infection." (PMID 23082961, 2012). "Specifically, we asked whether severe gut inflammation in immune-deficient hosts (NLRC4- or CYBB-deficient) could still be triggered by infection with an attenuated strain, S. TmSPI2." (PMID 41370284, 2025). "Indeed, CYBB-deficient mice exhibited higher bacterial loads in systemic organs compared to their CYBB-proficient littermates following infection with either S. TmWT or S. TmSPI2, while fecal burdens remained similarly high across all groups." (PMID 41370284, 2025). "In our earlier experiments with immune-deficient mice (NLRC4- and CYBB-deficient), we found that TTSS-2 virulence accelerated mucosal histopathology during the first 72h of infection." (PMID 41370284, 2025). "In HL-60 cells, infection with A. phagocytophilum results in AnkA translocation into the nucleus leading to decreased CYBB transcription." (PMID 23082961, 2012). "A highly significant and sustained increase in the expression of CYBB mRNA expression was detected in N'Dama after infection over the entire time course." (PMID 19409086, 2009). "The CYBB gene was observed to increase in mRNA expression in PBMC from both breeds relative to pre-infection over the time course." (PMID 19409086, 2009). "After S. TmWT infection, CYBB-deficient mice exhibited impaired epithelial regeneration capacity, whereas the CYBB-proficient controls exhibited no defect in epithelial regeneration capacity (judged by Ki67 + cells)." (PMID 41370284, 2025). "The catalytic subunit of the NADPH oxidase complex, CybB was unchanged during the infection." (PMID 34208904, 2021). "The study also observed no induction of TNF-α and IL-1β after 36 h of infection, but the antimicrobial response gene encoding cytochrome b-245 (CYBB) was up-regulated." (PMID 20854687, 2010). "In line with the results of the BM chimera sort and plating experiments, there were more GFP+ CYBB-/- neutrophils than GFP+ WT neutrophils in WT:CYBB-/- BM chimeric mice, both with Lpn-GFP infection and with Lpn-GFPind infection." (PMID 27105352, 2016). "A number of additional genes that play important roles in the immune response to infection were also increased in expression in response to trypanosome infection (GZMB, LYZ, CYBB and NCR3)." (PMID 19409086, 2009). "Interestingly, the expression of CYBB, JAK3, and GUCY2C was also turned off after vPdR-H30K-5U infection." (PMID 40006915, 2025). "Infection of Cybb-/- and Nox1-/- mice showed that the LPS-induced S. Tm bloom does not solely depend on CYBB or NOX1, suggesting potential redundancy in ROS generation pathways." (PMID 40113753, 2025).
tumor (148 papers, 2011 to 2026). "This state of low CYBB expression is associated with enhanced tumor-related inflammation and poor prognosis in patients." (PMID 40692778, 2025). "Accordingly, our GBM cohort confirmed a high expression of CYBB in the GBM tumor and was associated with mesenchymal features and poor clinical outcome." (PMID 37175412, 2023). "Survival analysis of these genes in tumour samples identified seven genes that were associated with prognosis, including ACSL5, HSD17B11, CCL5, NCF2, PSME1, ACTB, and CYBB." (PMID 40299520, 2025). "To confirm the intratumor heterogeneity observed in tumor cells at the single-cell level, on the basis of high CYBB expression observed in mesenchymal cells, we examined the transcriptomic profiles of bulk tumor cells." (PMID 37175412, 2023). "To validate the presence of aberrant CYBB expression in the clinical setting, we examined the tumor specimens of 65 patients with GBM from Taipei Medical University-Shuang Ho Hospital (TMU–SHH)." (PMID 37175412, 2023). "Immunostaining analysis indicated that the tumor specimens exhibited relatively high CYBB expression along with the overexpression of other well-known mesenchymal markers." (PMID 37175412, 2023). "In terms of cancer stemness characteristics, the depletion of CYBB reduced the invasion and migration capacities of U87MG-R cells and the number of tumor spheres, suggesting the crucial role of CYBB in mediating the EMT and self-renewal of TMZ-resistant cells." (PMID 37175412, 2023). "We also showed high tumor NOX2 (CYBB) expression that was tightly correlated with canonical M1 and M2 markers, and likely reflects TAMs, is also closely associated with many of the same cancer promoting programs linked to NOX4." (PMID 33557266, 2021). "Additionally, CYBB expression in cisplatin- and Erastin-treated subcutaneous tumor tissues was evaluated via IHC staining, which showed a positive correlation between p27 and CYBB expression." (PMID 41354340, 2025). "Therefore, single-cell profiling data indicated that the high expression of CYBB reflected mesenchymal signature activation in heterogeneous GBM tumor cells." (PMID 37175412, 2023). "Furthermore, the expression or activity of MDSCs-associated molecules (ARG1, CYBB, iNOS, IL-10, NCF4, and TGF-β2) were significantly decreased from GPR84−/− mice in both LLC and B16F0 tumor models." (PMID 37105980, 2023). "Nevertheless, we speculated that CYBB-mediated ferroptosis might induce immune cell activation, which enhances the anti-tumor immune responses in tumors." (PMID 35641509, 2022). "Meanwhile, the expression levels of CYBB were strongly positively associated with B cells, CD8 + T cells, CD4 + T cells, macrophages, neutrophils, and DCs (P < 0.001) and were only significantly negatively associated with tumor purity level (P < 0.001)." (PMID 36253777, 2022). "Tumor biopsies obtained during surgery were analyzed for expression of NCF2, CYBB, CD68, CD163, and NCAM1 by RT-PCR." (PMID 38598844, 2024). "Subsequently, we attempted to perform immunohistochemistry (IHC) staining for NRGs (CYBB, ITGB2, ITGAM, LILRB2, TLR2, and TLR7) in kidney sections from ANCA-GN patients and age- and sex-matched ccRCC patients with adjacent non-tumor tissues." (PMID 37465687, 2023). "Using value of IOD, quantification of immunohistochemical analysis showed that protein expressions of CYBB, IL1A, IL1B, and SLC25A5 were significantly higher in CESC tissues than in adjacent non-tumor tissues (P < 0.001)." (PMID 36253777, 2022). "We identified and verified that the expression levels of CYBB, CD86, and C3AR1 in tumor tissues were higher than those in normal tissues." (PMID 34950700, 2021). "On the TIMER and THPA websites, it is verified that the expression levels of CYBB, CD86, and C3AR1 genes in tumor tissues were higher than those in normal tissues." (PMID 34950700, 2021).